CD44 (CD44 molecule (IN blood group))
Diseases named in the same sentence as CD44 in open-access papers (continued):
Sharing a sentence is not in itself a finding about the gene and the disease.
breast carcinoma (continued). "We chose breast cancer cells MDA-MB-231 and SUM159 for this study as both are triple negative breast cancer cells (ER-, PR-, HER2-) with high levels of CD44 expression and contain a subpopulation of cells characterized as TICs." (PMID 25184276, 2014). "In this study, we determined the effects of NF-κB inhibition on the expression of its target genes, e.g., CD44, BCL-XL, and cMyc, as well as proliferation, migration and invasiveness of breast cancer cells." (PMID 25184276, 2014). "In view of intriguing evidence that various CD44 isoforms may associate with different histological parameters of breast cancer, it will be interesting to probe the relative raft/nonraft expression of these variants in response to cell migration in future studies." (PMID 24512624, 2014). "In this study, we demonstrate that microvascular endothelial cells express high levels of CD44 and HYAL2 and investigated their functional roles in cotrolling the formation of vessel-like structures and dissemination of breast cancer cells." (PMID 24614402, 2014). "To obtain breast CSCs, we have stained and sorted both NIPBC-1 and NIPBC-2 cell lines using antibodies against CD44 and CD24 cell surface markers taking MCF7 breast cancer cell line as positive control." (PMID 24502646, 2014). "We examined the dysregulation of the stem cell markers (Oct-4, Sox-2 and CD44) and the tumorsphere formation in HER2-overexpressing human breast cancer cell lines." (PMID 24297508, 2014). "ALDH+/CD44+ subpopulation can be sensitized by selective inhibition of ALDH activity using DEAB or all-trans retinoic acid, ATRA in breast cancer." (PMID 24884875, 2014). "Having considered Oct-4, Sox-2 and CD44 expression data, we wished to determine the tumorsphere formation capacity with HER2-overexpressing breast cancer." (PMID 24297508, 2014). "This is consistent with the finding that in breast cancer cells, Hyal-2 forms a complex with CD44 and the Na+–H+ exchanger 1 (NHE1), and HA degradation by Hyal-2 depends upon its interaction with CD44 at the membrane surface." (PMID 24653726, 2014). "HA binding to CD44 not only affects cell adhesion to extracellular matrix (ECM) components, but also stimulates a variety of tumor cell-specific functions leading to breast cancer progression." (PMID 24606718, 2014). "To assess the tumorigenic potential of PTK7 in BC and LN we compared the PTK7 expression level and co-expression with other breast cancer related genes (HER2, HER3, PAI1, MMP1, CK19, CD44)." (PMID 24409301, 2014). "Firstly we demonstrated that stem-like cells (CD44+/CD24lo/ESA+) were more migratory in both breast cancer cell lines and primary breast cancer samples, consistent with published research." (PMID 25277201, 2014). "Later, aldehyde dehydrogenase (ALDH) 1 expression and/or its activity were identified to be a marker for breast cancer stem/progenitor cells; fewer ALDH1 positive tumor cells than CD44+/CD24−/low tumor cells were required to generate tumors in vivo." (PMID 24558373, 2014). "For human breast cancer, the population of cells displaying CSC properties was identified and found to express the CD44+/CD24–\low cell markers." (PMID 25472619, 2014). "The same group later showed a similar genetic diversity between CD44+ and CD24+ cell populations for a subset of genetic markers commonly altered in breast cancer." (PMID 24998755, 2014). "Treatment of 14 breast cancer cell lines revealed that LSR+/CD44- lines were highly sensitive, LSR+/CD44+ lines were slightly sensitive, and LSR-/CD44+ lines were resistant to iota cytotoxicity." (PMID 24990559, 2014). "Regarding breast cancer cell lines such as MCF-7 and MDA-MB-231, a CD44+CD24− profile was described for CSC." (PMID 24586931, 2014). "CD44 and RHAMM can both signal through the Erk1/2 MAP kinase signaling pathway to regulate breast cancer motility, but also have different affects on cellular signaling." (PMID 24614402, 2014).
breast carcinoma (continued). "Herein we demonstrate a significant and novel non-mitotic role of Aurora-A kinase in the induction of tumor progression of ERα+ breast cancer xenografts through activation of EMT and the genesis of CD44+/CD24low/− cancer initiating cells." (PMID 24816249, 2014). "ME-CRCs isolated from MMTV-Neu transgenic mouse mammary tumors express high levels of HER2/neu, as well as tumor-initiating cell markers, such as CD44+, CD49f+, and ESA+ (EpCam)." (PMID 24831228, 2014). "Unfortunately, there is a paucity of data regarding the prevalence of the CD44/CD24 phenotype as a biomarker in breast tumor tissues and in relation to tumor clinicopathology among African-American and Hispanic women with breast cancer." (PMID 24167614, 2013). "Hyaluronan stimulates the interaction between CD44 and Nanog, an embryonic stem cell transcription factor, leading to activation of STAT3, and knockdown of STAT3 by siRNA blocks hyaluronan-induced breast cancer cell growth." (PMID 23326564, 2013). "We also determined that CD44 is overexpressed in 75% of BLC specimens and that the increase in expression compared to all other breast cancer specimens is statistically significant." (PMID 24324613, 2013). "Our results indicate that mammospheres isolated selectively from established breast cancer cells have suppressed VDR signaling, increased expression of CD44, and decreased sensitivity to 1,25D administration." (PMID 23341935, 2013). "This study investigated CD44 and CD24 cell surface markers as breast cancer CSC markers in vitro and in vivo." (PMID 23799994, 2013). "Recent studies showed that breast cancer cells undergoing EMT gain CSC properties including the ability to self-renew, tumorigenicity and expression of the CSC phenotype CD44+/CD24−/low." (PMID 23741479, 2013). "Enforced expression of DUSP4 reduced the CD44+/CD24− population in multiple BLBC cell lines in a MEK-dependent manner, limiting tumor formation, again underpinning the dual role of TGF-β in breast cancer." (PMID 24558636, 2013). "Clones of non-invasive CD44+CD24+ sorted cells from Ca1a, ZR75.1 and MCF7 breast cancer lines transplanted into immunocompromised mice gave rise to molecularly heterogeneous tumors that exhibited local invasion." (PMID 23986719, 2013). "For example, CD44+CD24− indicates breast cancer stem cells, whereas a pancreatic cancer stem cell phenotype is CD44+CD24+, and CD44+CD117+ is an ovarian cancer stem cell phenotype." (PMID 23626764, 2013). "Results have indicated that CD44 coimmunoprecipitates and colocalizes with cell surface RHAMM in invasive breast cancer cells, acting together in a HA-dependent autocrine mechanism to regulate signaling through ERK1,2, leading to an increase cell migration." (PMID 24083250, 2013). "In the epithelial-like T47D breast cancer cells, IL6-induced EMT generated CD44+ cells with stem-like properties." (PMID 23776679, 2013). "Further, the impact of ATG4A expression on sphere formation of breast cancer cell lines from different sub-types, namely basal MDA-MB-231 (CD44+/CD24-) and luminal MCF-7 cells (CD44-/CD24+) was analysed." (PMID 24229464, 2013). "Notch1 inhibition alters the CD44+/CD24− population and reduces the formation of brain metastases from breast cancer." (PMID 23651443, 2013). "ESRP1 was shown to regulate a switch in CD44 alternative splicing, an event required for EMT and breast cancer progression." (PMID 23887935, 2013). "Flow cytometry with CD44 and CD24 markers was used to sort breast cancer MCF7 cells for scanning electron microscopy (SEM), tumor cell invasion assay, and nude mouse xenograft assay." (PMID 23799994, 2013). "In breast cancers, a subset of the cells with high aldehyde dehydrogenase (ALDH1) activity and CD44+/CD24−/low phenotype has been characterized as CSCs population with tumorigenic and radioresistant phenotype." (PMID 23741479, 2013).
breast carcinoma (continued). "Overall, ALDH+ and CD44+/CD24− cells are more frequent in basal-like/mesenchymal and basal-like breast cancer respectively, whereas luminal tumors are enriched in ALDH− and CD44+/CD24− cells." (PMID 24376586, 2013). "Breast cancer cells with CD44+CD24− were identified as CSCs, which form heterogeneous tumors with CD44+/− and CD24+/− phylogeny." (PMID 23626764, 2013). "Accordingly, breast cancer cells displaying high ALDH activity and the CD44+CD24− phenotype were highly tumorogenic compared to cells that did not display the CD44+CD24− pattern." (PMID 24305653, 2013). "Another cell adhesion molecule, CD44, which interacts with P-gp via FERM domain binding proteins, was also assessed in understanding the basis of the transfer selectivity observed for breast cancer-derived DXMPs." (PMID 23593486, 2013). "The ALDH+/CD44+/CD24− subpopulation of MDA-MB-231 and SUM159 breast cancer cells expressed higher levels of P-STAT3 compared to the un-separated or ALDH−/CD44+/CD24+ subpopulations." (PMID 24376586, 2013). "The CD44+CD24– cell population is capable of self-renewal and generating tumors resembling breast cancer." (PMID 24331293, 2013). "CD44+CD24− cells have been proposed to represent cancer stem cells in breast cancer, as well as in head and neck squamous cell carcinoma (the latter includes an ALDH1+CD44+CD24− stem cell subset)." (PMID 23484127, 2013). "Surface CD44 and CD24 expression were assayed in established breast cancer lines and in seven patient-derived TNBC dissociated tumour cultures (DTs)." (PMID 23982961, 2013). "For example, Notch1 inhibition alters CD44+/CD24− population and reduces the formation of brain metastases from breast cancer." (PMID 23651443, 2013). "Sorafenib eliminates EZH-induced BTIC expansion, decreases the number of CD44+CD24−/low cells, and blocks the formation of precancerous mammospheres in human breast cancer cells." (PMID 23314174, 2013). "The CD44+/CD24- phenotype can be detected by immunohistochemistry and is related to the most aggressive tumor grades in canine mammary neoplasms." (PMID 24119896, 2013). "In contrast to observations in the normal mammary gland, Meyer and colleagues have recently shown that, in the context of ER- breast cancers, CD133 enriches for TICs when used in conjunction with CD49f (integrin α6) and CD44." (PMID 22225988, 2012). "We have shown that tetracycline-induced expression of CD44 in the noninvasive, luminal MCF-7 breast cancer cell line is alone sufficient to induce cell invasion in response to HA in vitro." (PMID 22621373, 2012). "Here we have investigated the effect of hypoxia on CD44 and two of its isoforms in MDA-MB-231 and SUM-149 triple negative human breast cancer cells and MDA-MB-231 tumors using imaging and molecular characterization." (PMID 22937154, 2012). "Recently we identified that CD44, a transmembrane cell adhesion receptor known to interact with growth factor receptors, is upregulated in tamoxifen-resistant (TamR) MCF7 breast cancer cells." (PMID 23039365, 2012). "Autophagy addiction underlying the primaryresistance of HER2 gene-amplified breast cancer cells to HER1/2 targeting therapies may depend, atleast in part, on the previously unrecognized ability of autophagy to regulate atrastuzumab-unresponsive CD44+CD24−/low mesenchymal cellular state." (PMID 23307622, 2012). "Using this method, the breast carcinoma cells displayed four distinct staining patterns on the basis of cell membrane positivity (CD44+/CD24−, CD44+/CD24+, CD44−/CD24+ and CD44−/CD24−)." (PMID 23028444, 2012). "In several in vitro breast cancer models, the CD24+/CD44+ population declined but the CD24−/CD44+ fraction increased after herceptin treatment." (PMID 23042145, 2012). "In breast cancer cells, Twist expression correlates with an increase of TIC parameters such as CD24−/CD44+ expression, enhanced ALDH1 activity and a higher SP fraction." (PMID 23042145, 2012).
breast carcinoma (continued). "Breast cancer samples displayed four distinct cell sub-populations based on their membrane expression pattern (CD44+/CD24−, CD44+/CD24+, CD44−/CD24+ and CD44−/CD24−), and merged images showed excellent CD44/CD24 co-localisation, when present." (PMID 23028444, 2012). "The genes CD44 (P = 0.050), RARB (P = 0.026), ATM (P = 0.017) and STK11 (P = 0.040) also showed less frequent methylation in male breast cancer." (PMID 22765268, 2012). "Compared to MCF-7, both the upregulation of CD44+CD24–/low subpopulation ratio and IC50 of adriamycin indicated that breast cancer stem cells displaying chemoresistance would also play an important role in tamoxifen resistance." (PMID 23554768, 2012). "In breast cancer cells, the metastatic cell state is strongly correlated to EMT and the CD44+/CD24− stem cell phenotype." (PMID 22408395, 2012). "Since then, the tumourigenic potential of the CD44+/CD24− profile has been repeatedly confirmed in primary tissues and in human breast cancer cell lines." (PMID 23028444, 2012). "For example, analysis of the genomic composition of CD44+CD24− and CD44−CD24+ breast carcinoma cells has revealed the existence of unexpected clonal divergence between the two populations in some tumor samples." (PMID 22408433, 2012). "We demonstrate that Six1 is overexpressed in the CD24low/CD44+ TIC population from human luminal breast cancers, and that it can induce TICs when overexpressed in luminal breast cancer cells via its ability to activate both TGF-β and ERK signaling." (PMID 22765220, 2012). "The ability of the conserved regions to direct gene expression was tested using three previously characterized human breast cancer cells, MDA-MB-231, SUM159, and MCF7, each with a different CD44/CD24 expression profile." (PMID 23226410, 2012). "In breast cancer, the CD24−/low/CD44+ marker combination has been shown to identify in vivo tumorigenic cell subpopulations, although the percentage of the subfraction did not correlate with the in vivo tumorigenicity." (PMID 23042145, 2012). "A high percentage of BCSCs enriched with CD44+CD24-/low phenotype was found harbored in basal-like tumors and the phenotype was observed in ‘triple-negative’ breast cancer that responded poorly to chemotherapy." (PMID 23046710, 2012). "From the MCF-7 and MDA-MB231 breast cancer cell lines and primary culture of patient breast cancer cells, we isolated by flow cytometry a CIC subset of cells with the CD44+/CD24−or low phenotype." (PMID 21935375, 2011). "As exemplified in breast cancer for example, putative CSC (CD44+/CD24−) can be enriched in-vitro by isolating mammospheres from suspension cultures." (PMID 21304586, 2011). "Independently, both CD44+ and CD24+ breast cancer cell populations have been shown to be involved in the metastatic process." (PMID 24212798, 2011). "Exogenous HA oligosaccharides blocked endogenous HA binding to CD44, resulting in the inhibition of PI3K/Akt signalling pathway in murine mammary carcinoma cells." (PMID 22045192, 2011). "The present study showed that putative CSCs identified by CD44/CD24 and ALDH1 immunohistochemistry significantly increased after PST in human breast cancer tissue." (PMID 21559013, 2011). "In an initial study we used the ATM inhibitor KU-55933 and showed significantly decreased radiation resistance of the CD44+/CD24− subset isolated both from of the MDA-MB-231 cell line and the primary culture of patient breast cancer cells." (PMID 21935375, 2011). "The differences in CD44+/CD24− tumour cell proportions and ALDH1 positivity between the subtypes of breast cancer were statistically significant." (PMID 21559013, 2011). "To estimate the model parameters, we then designed a long-term sphere culture of breast cancer MCF-7 stem cells, since MCF-7 cell line followed the CSC model and its CSC marker, CD44+CD24−/low, was generally confirmed and easily detected by flow cytometry." (PMID 22110580, 2011).
breast carcinoma (continued). "An association with survival has been demonstrated by one study and gene signatures derived from CD44+ primary breast cancer cells and CD44+CD24- breast cancer cells (from xenografts or pleural effusions) have also been shown to correlate with outcome." (PMID 22112299, 2011). "Here we show that cells affected by FTI treatment express breast cancer stem cell markers ALDH1 and CD44." (PMID 22046561, 2011). "The growth of the breast cancer cell lines MCF-7 and MDA-MB-231 as mammospheres has demonstrated the enrichment in the mammospheres of CD44+/CD24−/low−/EAS+ cells and the cells in the mammospheres are more radiation resistance than cells grown in monolayer." (PMID 21935375, 2011). "A close relationship between the percentage of cells with CSC phenotype (CD44+/CD24−) in the primary tumor and the development of metastasis in breast-cancer was recently reported." (PMID 21304586, 2011). "At present most of what we know about the role of CSC in breast cancer metastasis has been based on ALDH-positive, CD133-positive or CD44+CD24−/low breast CSC populations." (PMID 24212798, 2011). "CD44 and CD133 are also over-expressed in multicellular spheroids (called mammospheres), derived from breast cancer tissues and cell lines." (PMID 21092249, 2010). "Initially, CD44+CD24−/low cells were proposed to exhibit CSC properties and are regarded as CSC for breast cancer." (PMID 24281171, 2010). "Analysis of several breast cancer cell lines revealed the co-expression of Gli-2 and SLUG in only breast cancer cell lines with CD44+/CD24- phenotype." (PMID 20691079, 2010). "To determine the hierarchical organisation of breast cancer cell lines, we analysed the tumourigenic potential of the CD24−/low/CD44+ and CD24+/CD44+ cell populations of HCC1954 and MCF7 cell lines." (PMID 19997106, 2010). "In breast cancer cells, the metastatic cell state is strongly correlated to epithelial-to-mesenchymal transition (EMT) and the CD44+/CD24- stem cell phenotype." (PMID 20696077, 2010). "The percentage of BT-ICs in breast cancer cell lines and primary breast tumors was determined by ALDH1 enzymatic assay, CD44+/CD24− phenotype and mammosphere formation assay." (PMID 21187973, 2010). "Based on our data of flow cytometry, the CD44+/CD24− and ALDH1+ primary breast cancer cells varied from 1.8% to 48% and 0.4% to 23.6% respectively, which was verified by ALDH1 immunohistochemical staining." (PMID 21187973, 2010). "The discovery of the CD44/CD24 phenotype and its relation with unfavorable prognosis in TN breast cancer disease also makes CD44 targeting an attractive therapeutic alternative." (PMID 21050424, 2010). "In breast cancer (BC), a CD44+/CD24–low/Lin− cell population was first identified as T-ICs." (PMID 20145614, 2010). "In breast cancer cell lines, the ALDEFLUOR-population has been divided by the use of CD44+, CD24- and CD133." (PMID 19555472, 2009). "In an effort to understand the dynamics of CD24 expression in breast cancer cell lines, cells were sorted based on their CD44 CD24 expression and the CD44/CD24 expression of their progeny was evaluated." (PMID 19906290, 2009). "The IGS consists of 186 genes which are overexpressed in breast cancer stem cells identified by high expression of CD44 and low expression of CD24 (CD44+CD24-/low), compared to normal breast epithelial cells." (PMID 19664271, 2009). "Since then, the CD44/CD24 profile has been widely investigated in both primary tissues and established breast cancer cell lines." (PMID 19906290, 2009). "Of interest, certain expression levels of CD24 and CD44 are considered as breast cancer stem cell markers and a significant reduction of CD24 and CD44 surface markers is observed during HMEC aging." (PMID 19751512, 2009). "The interacting protein CD44 and EpCAM were part of the CSC signature in not only breast cancer but also colon." (PMID 18852874, 2008).